IL1B (interleukin 1 beta)
Diseases named in the same sentence as IL1B in open-access papers (continued):
Sharing a sentence is not in itself a finding about the gene and the disease.
Crohn disease (continued). "Clinically, oral butyrate is effective for inducing clinical improvement/remission in Crohn’s disease, which may exert its action through downregulating mucosal levels of NF-κB and IL-1β." (PMID 34680413, 2021). "High concentration of IL-1β and IL-18 cytokines is observed in patients with Crohn’s disease." (PMID 34630405, 2021). "Behcet's disease might also resemble Crohn's disease as they both have polygenic auto‐inflammatory factors where IL‐1β increases." (PMID 33363738, 2020). "Moreover, butyrate decreases the intestinal expression levels of tumor necrosis factor-α, IL-1b, and IL-6 in patients with Crohn’s disease." (PMID 28904265, 2017). "IL1B -511 C/T polymorphism was found to be associated with temporal lobe epilepsy (TLE) in hippocampal sclerosis, chronic gastritis and gastric ulcer, polycystic ovarian syndrome, Crohn’s disease and Vitiligo." (PMID 27749914, 2016). "Thus, the effect of pentoxifylline was investigated on intestinal inflammation in IBD, showing that pentoxifylline downregulates in vitro TNF-α and IL-1β production by PBMCs and by intestinal organ cultures from patients with Crohn’s disease and ulcerative colitis." (PMID 36142518, 2022). "Moreover, the inhibition or impairment of ATG16L1 was associated with autophagy block and incapacity to control inflammasome proteolysis in autophagolysosomes resulting in exacerbated IL-1β secretion, inflammation and necrotic cell death in the context of epithelial cells and Crohn’s disease." (PMID 29326705, 2017). "In another mouse model, a NOD2 mutation potentiated NF-κB activity and IL-1β processing, suggesting that NOD2 may act as a positive regulator of NF-κB activation and IL-1β secretion, thereby increasing the intestinal inflammation observed in Crohn’s disease patients." (PMID 23162548, 2012). "Genetic studies have identified candidate loci for Crohn's disease susceptibility among autophagy genes, while experiments in murine macrophages from ATG16L1 deficient mice have shown that disruption of autophagy increases processing of IL-1β and IL-18 through an inflammasome-dependent manner." (PMID 21490934, 2011). "We painted the landscapes of monocyte-macrophages and identified 5 distinct subsets including monocytes, C1QB+ macrophages, HSPA1B+ macrophages, IL-1B+ macrophages, and TMSB4X + macrophages in the intestinal mucosa from Crohn’s disease patients." (PMID 39095853, 2024). "Activation of the RhoA/ROCK pathway stimulates TNF-α and IL-1β production, with a positive correlation observed between RhoA and TNF-α in the inflammatory tissues of Crohn's disease patients." (PMID 38491049, 2024). "For example, there is a positive correlation between RhoA and TNF-α in the intestinal inflammatory tissues of Crohn’s disease patients, and RhoA/ROCK pathway activation stimulates the production of TNF-α and IL-1β." (PMID 38355537, 2024). "Crohn’s disease (CD) involves activation of mast cells (MC) and NF-кB in parallel with the PPAR-α/NLRP3 inflammasome/IL-1β pathway in the inflamed colon." (PMID 38283356, 2023). "ELISA was carried out to examine the expression of TNF-α, IL-1β, IL-6, CRP, SSA, AAT, AAG and HPT in the peripheral blood of patients with Crohn’s disease." (PMID 35422450, 2022). "In a Crohn’s disease model, CXCL10 blockade reduces serum IL-12p40, IL-2, IFN-γ, IL-1α, IL-1β, and TNF-α." (PMID 29910805, 2018). "Moreover, oral administration of butyrate in patients with mild to moderate Crohn's disease induces clinical remission through ESR, NF-κB, and IL-1β reduction." (PMID 40123849, 2025). "This view derives from the fact that despite the existence of agents that efficiently block IL-1β activity there are no published studies showing that these agents have therapeutic value in the ordinary patient with Crohn’s disease." (PMID 41246319, 2025).
Crohn disease (continued). "Both HS and Crohn’s disease have shared genetic and cytokine profiles, including the involvement of cytokines such as IL-1β and TNF-α, indicating that HS and Crohn’s disease may share therapeutic targets." (PMID 39337688, 2024). "When the gingival crevicular fluid Th17 cytokine protein expressions were analyzed in Crohn’s patients, similar expression profiles of IL-1β, IL-6, IL-10, IL-12p40, IL-12p70, IFN-γ, and tumor necrosis factor (TNF)-α were observed in Crohn’s disease patients and in systemically healthy controls." (PMID 38246944, 2024). "In another study in a murine model of Crohn's disease, UCN could control inflammatory diseases by inhibiting a wide range of inflammatory cytokines such as TNF-α, IFN‐γ, IL-6, IL-1α, IL-1β, IL-12, IL-18, IL-17, and IL-15." (PMID 35419072, 2022). "In regard to IL-1β and TNF-α regulation by calcitriol, it has been demonstrated that this hormone enhanced muramyl dipeptide-induced TNF-α production in monocyte-derived dendritic cells from Crohn's disease patients." (PMID 31093512, 2019). "For instance, the creeping fat in patients with Crohn’s disease (CD) has been referred to as the inflammatory mesenteric fat hypertrophy mediated by a rise in proinflammatory adipokines, including TNF-α, TWEAK, leptin and IL-1β." (PMID 28425943, 2017). "Fractalkine expression is upregulated by inflammatory cytokines (IFN-γ, IL-1β and TNF-α) or by direct leukocyte contact, and has been detected in intestinal epithelial cells and endothelial cells both in normal small intestine and in active Crohn’s disease mucosa." (PMID 37645250, 2023). "In a related vein, this discovery also mandates that Crohn's disease patients not responsive to conventional therapies be investigated to determine if excess IL-β secretion is present and would therefore benefit from administration of an IL-1β blocker." (PMID 30455704, 2018). "Because pentoxifylline, acting on TNF-α and IL-1β, is a non-selective PDE inhibitor, PDE activities were investigated in the human normal mucosa and inflamed mucosa of patients with Crohn’s disease." (PMID 36142518, 2022). "The production of IL-1β and IL-18 is increased in the absence of functional ATG16L1 in a mouse model of Crohn’s disease." (PMID 25409294, 2014).
Autoimmunity (99 papers, 2010 to 2026). The occurrence of an immune reaction against the organism's own cells or tissues. "HFD diet causes the production of proinflammatory cytokines, IL-6, IL-1β, and Th17, which causes gut inflammation and CNS autoimmunity, finally leading to MS." (PMID 41008984, 2025). "It is possibly caused by the high profile of inflammation such as IL-1β in these subjects with T1D and other autoimmune- and inflammation-associated diseases." (PMID 39125908, 2024). "Although it functions to initiate appropriate innate and adaptive immune responses, aberrant expression of IL-1β has been implicated in the development of many diseases, including autoimmune conditions, metabolic disorders, and cardiovascular disease." (PMID 37441079, 2023). "More recently, TNFα has been reported to induce the inflammasome-independent production of IL-1β, causing autoimmunity." (PMID 35269395, 2022). "This multiprotein complex has been associated with organ-specific autoimmunity since a wide spectrum of endogenous danger signals can activate inflammasome products, including IL-1β, triggering adaptive immunity pathways." (PMID 34697538, 2021). "It has recently been reported that TNFα induces the inflammasome-independent production of IL-1β, causing autoimmunity." (PMID 33562074, 2021). "IL-1b is a key pro-inflammatory cytokine that has been implicated in pain, inflammation, and autoimmune conditions." (PMID 32585863, 2020). "Conversely, IBD patients who carry an autoimmunity-associated PTPN22 variant have increased IL-1β levels." (PMID 28561062, 2017). "Recent studies have shown IL-1β as an important mediator of Th17 response in humans and is often associated with autoimmunity." (PMID 21779356, 2011). "Effective down-modulation of immune responses is critical for physiological immune responses and to avoid autoimmunity and autoinflammatory diseases such as those caused by deregulated increased secretion of IL-1β due to inflammasome hyper-activation." (PMID 21611201, 2011). "Higher levels of VEGF-A could serve as a biomarker for viral RNA persistence in the semen, whereas higher levels of MCP-1, IL-1β, and M-CSF might indicate the presence of another underlying biological mechanism, such as autoimmunity or immune dysregulation." (PMID 40081398, 2025). "The IL-1β-induced cytokines promoted inflammation and autoimmunity to cause GO formation." (PMID 37109536, 2023). "Similar increases in systemic IL-1β have been observed in patients with RA, and the success of clinical trials for anti-IL-1β therapeutics demonstrates the significant and pathogenic role of IL-1β during autoimmunity." (PMID 32993051, 2020). "On the contrary, the autoimmunity-associated PTPN22 variant enhanced IL-1β secretion." (PMID 32751912, 2020). "IL-1β is a pro-inflammatory cytokine implicated in inflammation, pain and autoimmune conditions." (PMID 31191313, 2019). "Conversely, knockdown of DDX6 by siRNA was successful in pseudonormalization of IL-1β levels, suggesting both a pathway for rapamycin-treatment of this disorder and new targets for pharmacological intervention against autophagy-related IL1β-associated autoimmunity." (PMID 30154791, 2018). "IL-1β is considered to be an endogenous pyrogen and also plays a vital role in promoting a variety of innate immune processes associated with infection, inflammation and autoimmunity." (PMID 28402258, 2017). "For example, autoimmune conditions often require azathioprine, leflunomide, or T/B cell blockade, while autoinflammation can be managed with colchicine or cytokine (IL-1β, IL-18, IL-36) inhibitors." (PMID 41550415, 2026). "Firstly, the released cytokines from MDSCs play a pro-inflammatory and pathogenic role in autoimmunity, including Arg-1, NO, ROS, IFN-γ, and IL-1β." (PMID 37733169, 2024). "Elevated levels of pro-inflammatory cytokines such as IL-6, TNF-α, and IL-1β are frequently observed in adenomyosis, creating an environment conducive to autoimmunity." (PMID 39518312, 2024).
Autoimmunity (continued). "We have shown previously, that serum of autoimmune patients containing ANAs or of pristane-induced SLE mice boosts the IL-1β response of recipient cells." (PMID 36936231, 2023). "IL-1β has many biological functions, which are closely related to pain, inflammation, and autoimmunity, and is involved in neuroprotection, tissue remodeling and repair, and the regulation of IL-6 and TNF-α, etc.." (PMID 37109624, 2023). "IL-1β induces the differentiation of T helper 17 (Th17) cells, which promote inflammatory responses and mediate tissue damage, and participate in MG autoimmunity by regulating B-cell tolerance and the production of AChR-Ab." (PMID 37441608, 2023). "Inflammatory signaling is; however, intricate and their mediators including TNF, IL-1β, IL-6, and interferons often co-occur in conditions such as aging, cancer, and autoimmunity." (PMID 36968066, 2023). "It is likely that the stage of disease development and degree of thyroid dysfunction are important in shaping the profile of secreted cytokines (in this case, IL-1β) by cells participating in the autoimmunity process." (PMID 35889825, 2022). "While IL-1β is a proinflammatory cytokine that has been involved in inflammation, pain, and autoimmune conditions." (PMID 35576032, 2022). "Local injection of CFA resulted in an increase of TNF-α, IL-1β, and IL-6 levels due to activation of autoimmunity cells which aggravated complete inflammation." (PMID 35193490, 2022). "IL-1β is central to the pathogenesis of many chronic inflammatory diseases such as rheumatoid arthritis, type 2 diabetes, gout, and a vast range of autoimmune conditions." (PMID 34858390, 2021). "Th17 cells are a subset of T helper cells related to autoimmunity and inflammation, which have IL-1β receptors and can secrete cytokines such as IL-17 and IL-22 under the stimulation of IL-1β." (PMID 34093086, 2021). "Treatment with OA also reduced the indices of inflammation and autoimmunity in colon tissues, (i.e., increased TNFα, IL-1β, IL-23, IL-17A, and KC; and reduced IL-13, IL-33, and IL-25)." (PMID 33246492, 2020). "The activation of NLRP3 inflammasome-IL-1β pathway in keratinocytes contributes to the melanocyte death via autoimmunity-dependent manner in vitiligo." (PMID 32754591, 2020). "In the present study, we found elevated levels of NLRP3 inflammasome and inflammatory cytokines (IL-1β, IL-6, IL-17) in CSF in patients with autoimmune GFAP astrocytopathy." (PMID 31681133, 2019). "Our findings implicate IL-1β and its downstream IL-17 signaling in the tissue fibrosis, inflammation, and autoimmunity involved in SSc." (PMID 30042768, 2018). "Inefficient clearance of cellular debris in SLE results in the elevation of reactive oxygen species and mediates NLRP3 activation, and the accumulation of cytosolic self-DNA in autoimmunity triggers AIM2 inflammasome-mediated IL-1β production." (PMID 28266599, 2017). "Then, pro-IL-1B is activated by caspase 1 at the inflammasome, and both cytokines promote autoimmunity." (PMID 26064998, 2015). "Th17 cells, a subset of Th cells involved in autoimmunity and inflammation, possess IL-1β receptors and secrete cytokines such as IL-17 and IL-22 in response to IL-1β stimulation." (PMID 23970818, 2013). "Rac-1 is directly implicated in the activation of caspase-1, which is crucial for processing and secretion of the proinflammatory cytokines IL-1β and IL-18, promoting autoimmunity." (PMID 24147031, 2013). "Earlier, we have shown that GM-CSF-exposed CD8α− DCs that express low levels of pro-inflammatory cytokines IL-12 and IL-1β can induce Foxp3+ Tregs leading to suppression of autoimmunity." (PMID 21779356, 2011). "Elevated levels of IL-6, TNF-α, and IL-1β contribute to chronic inflammation and antibody production, whereas decreased production of IL-10 may explain the failure to suppress autoimmunity in ITP." (PMID 40922302, 2025).
Autoimmunity (continued). "It is known that cytokines have different functions in different contexts and cells, and we therefore suggest that IL-1β might function differently in immune cells in the context of autoimmunity or cancer." (PMID 39576827, 2024). "IL-1β and IL-6 have a pathological effect on chronic inflammation and autoimmunity." (PMID 35548349, 2022). "Rat mononuclear phagocytes may be able to utilise an ‘alternative inflammasome’ pathway to produce IL‐1β independently of P2RX7, which may account for the susceptibility of P2RX7 KO rats to inflammation and autoimmunity in glomerulonephritis." (PMID 35239186, 2022). "MC-secreted cytokines and chemokines encoded by IL1B, TNF, CCL3, and CCL4, all of which contribute to autoimmunity and inflammation, may stimulate other cell populations expressing their homologous receptors." (PMID 36301664, 2022). "Although the expression levels of these inflammation cytokines induced by TBI are gradually suppressed by autoimmunity in the vehicle control group over time, especially 7 days post injury, there are still significant differences in IL-1β and IL-6 levels between the Sham and TBI groups." (PMID 33414464, 2021). "The autoimmunity-associated PTPN22 variant promotes NLRP3 activity, caspase-1 activation, and secretion of IL-1β and IL18, which might—at least partially—explain the pro-inflammatory character of this PTPN22 variant in T1D, RA and SLE development." (PMID 32751912, 2020). "Nevertheless, whether keratinocyte-derived IL-1β damages melanocytes in an autoimmunity-independent way and whether TR could ameliorate the melanocyte damage via inhibiting the NLRP3-IL-1β pathway in keratinocyte still are not clear." (PMID 32754591, 2020). "The presence of autoimmunity associated PTPN22 variant in mice (PTPN22-619W) resulted in dephosphorylation and activation of NLRP3, while loss of PTPN22 resulted in decreased NLRP3 mediated IL-1β secretion." (PMID 30915320, 2019). "Some agents targeting IL-1β, such as IL-1 receptor antagonist, soluble decoy IL-1 receptor and neutralizing monoclonal antibodies against IL-1, have been approved in clinics to treat autoimmunity or inflammatory diseases." (PMID 31379842, 2019). "The concept is well suited for immune mechanisms, demonstrated by the induction of inflammasome activation by TLR4, accompanied by the simultaneous induction of autophagy to degrade IL-1β, resulting in mechanisms to optimize pathogen control and yet avoid autoimmunity." (PMID 30154791, 2018). "Further studies, prompted by the recent finding of a role for autophagy in modulation of inflammasome-related IL-1β levels demonstrated that the reduced autophagy activity in these patients resulted in elevated levels of IL-1β, suggesting an etiology of the patient’s autoimmunity." (PMID 30154791, 2018). "MSC inhibit the NLRP3 inflammasome activation and IL-1β release by DCs, which might prevent autoimmunity induction." (PMID 29434214, 2018). "Identification of the molecular players involved in IL-1β production resulting from DC-T cell interactions might uncover novel targets to treat autoimmunity as well as auto-inflammatory diseases." (PMID 30093707, 2018). "In particular, IL-1β is an inducible cytokine that is, generally, not produced by healthy cells and it is implicated in pain, inflammation, and autoimmune conditions." (PMID 29912150, 2018). "It is unknown if the early events leading to IL-1β expression are required for silica-induced autoimmunity." (PMID 27014276, 2016). "IL-1β has been shown to play a pivotal role in autoimmunity." (PMID 26071315, 2015). "Indeed, Th17 cells, whose development in human is mainly induced in response to IL-23 and IL-1β, release interleukin-17A that exhibits potent proinflammatory properties in animal models of autoimmunity, including EAU." (PMID 24312163, 2013). "Therefore, miR-708 may be a crucial TNFα/IL-1β signaling-suppressing miRNA involved in early stage inflammatory-related oncogenesis and autoimmunity." (PMID 33776573, 2021).